ALB (albumin)
Diseases named in the same sentence as ALB in open-access papers (continued):
Sharing a sentence is not in itself a finding about the gene and the disease.
malnutrition (continued). "On the contrary, there was a negative association between GLIM-diagnosed malnutrition and differentiation degree, adjuvant chemotherapy, KPS score, BMI, MAMC, HGS/W, CC, total protein, albumin, prealbumin, hemoglobin, red blood cell and platelets counts (all p < 0.05)." (PMID 36501196, 2022). "A low SIS indicated low LMR and/or albumin levels, which may increase nonspecific inflammation, immune system dysfunction, and malnutrition." (PMID 36221349, 2022). "Therefore, albumin was no longer recommended for identifying malnutrition by the Academy of Nutrition and Dietetics (AND) and ASPEN." (PMID 36742004, 2022). "Shen suggested that albumin and prealbumin rather than the body mass index may be beneficial for assessing malnutrition." (PMID 35153714, 2021). "Our results suggest that malnutrition is a significant clinical manifestation in gynecological cancer patients who may benefit from TPN treatment for reduced hospitalization and improved serum albumin levels." (PMID 35127741, 2021). "Adding to these findings, we also demonstrated, as expected, that when sarcopenia and malnutrition occurred concomitantly (group sarcopenia and malnutrition), all parameters of nutritional status, except for albumin, were worse when compared with the group no-sarcopenia and no-malnutrition." (PMID 34604279, 2021). "Furthermore, it has been demonstrated in older patients with hematological malignancies that individuals with malnutrition had more often inflammation (as measured by elevated CRP and low albumin) and suffered from impairments in mood, performance status, and fatigue." (PMID 34476573, 2021). "Hypoalbuminaemia occurred because albumin is a negative acute‐phase protein, and it might be worsened by malnutrition and improper digestion due to pain and adhesions." (PMID 32810898, 2021). "Although not statistically significant as a risk factor, malnutrition might contribute to HAEC incidence by its correlation with low hemoglobin and albumin level." (PMID 34485196, 2021). "As total cholesterol level, serum albumin level and lymphocyte count were already considered by the malnutrition-based scores, these variables were not taken into account in the multivariate analysis that included CONUT and PNI scores, regardless of their significance in the univariate analysis." (PMID 34067233, 2021). "Nutritional status was defined primarily by serum albumin (SA) concentration (low, <45 g/L [malnourished]; high, ≥45 g/L [well-nourished]), and secondarily by the prognostic nutritional index (PNI) and Global Leadership Initiative on Malnutrition (GLIM) criteria." (PMID 34061848, 2021). "However, because dietary restrictions do not always lead to serum albumin reduction, it has been suggested that the significance of inflammation outweighs the effects of malnutrition when measuring serum albumin levels." (PMID 33669609, 2021). "This assumption may as well apply to albumin, an indicator of malnutrition; RS2 could neither increase nor reduce its serum levels." (PMID 33437217, 2021). "However, since many disease processes can alter prealbumin and albumin levels, these parameters alone do not represent reliable serum markers for malnutrition." (PMID 34068498, 2021). "Serum albumin is not a good indicator of nutritional status since it does not change in response to changes in nutrient intake and is neither sensitive nor specific enough to evaluate malnutrition." (PMID 32384662, 2020). "Also, serum albumin concentrations do not change in response to short-term changes in nutrient intake and in states of malnutrition." (PMID 32708140, 2020). "Third, we did not exclude those who were received infusions of human albumin to treat malnutrition." (PMID 32602387, 2020). "In addition, only one19 of the 27 unique articles isolating albumin claims that albumin is not a reliable test of choice for identifying malnutrition." (PMID 33939393, 2020).
malnutrition (continued). "FFMI could determine the malnutrition that could not be determined by the BMI (58.8%), albumin (90.6%), NRS2002 (50.0%), and PG-SGA (55.6%)." (PMID 32328493, 2020). "However, serum albumin level is also reduced in patients with locally advanced or metastatic malignancies irrespective of the presence of malnutrition." (PMID 31931816, 2020). "However, as the pathological mechanisms of ESLD (i.e., hepatic insufficiency and/or malnutrition) may negatively influence CRP and ALB production, cirrhotic patients have always been excluded from previous studies." (PMID 31821367, 2019). "Furthermore, the weight loss that was used to define malnutrition negatively correlated with PALB, but not with ALB." (PMID 31379941, 2019). "Furthermore, rather than serving as a marker of malnutrition, a decreased pre-albumin level has been identified as an inflammatory indicator and is considered a novel and feasible predictor of unfavorable OS in gastric cancer patients." (PMID 31772657, 2019). "Raised albumin suggests malnutrition is not a main factor in ME/CFS in this study." (PMID 30974900, 2019). "Moreover, we did not observe lower BMI levels or lower albumin levels in the patient group, suggesting that, despite lower intake in patients compared with controls, patients did not exhibit malnutrition by standard measures." (PMID 30781687, 2019). "Inclusion of patients with suspected wall thickness but exclusion of ones with verified gastric cancer based on CT findings might have resulted in the finding that low albumin level due to malnutrition in our patients was not an independent variable." (PMID 31827513, 2019). "All of the patients had no significant medical histories such as liver cirrhosis or malnutrition which could affect coagulofibrinolytic parameters and serum albumin levels." (PMID 30078997, 2018). "The pattern of lower prealbumin and albumin in the coinfected group in the absence of inflammation may be suggestive of malnutrition and would require further investigation." (PMID 30065944, 2018). "In addition, frail older patients who were hospitalized had lower levels of albumin, which is a marker of malnutrition, and higher levels of CRP and IL-6 than non-frail individuals." (PMID 30249038, 2018). "Increased albumin turnover in peritoneal dialysis patients with ongoing losses of protein into dialysate results in hypoalbuminemia, which is the result of chronic inflammation rather than malnutrition." (PMID 30235860, 2018). "Importantly, both albumin levels and BMI did not suggest malnutrition in non-phosphate binder users (albumin 42.4 ±3.2 g/L and BMI 26.2 ±4.4 kg/m2 versus 40.3 ±3.4 g/L and 25.4 ±4.8 in kg/m2 in phosphate binder users)." (PMID 30161193, 2018). "The FE-1 levels reduced along with the increasing severity of CHF and the decreasing nutritional parameters (such as BMI, albumin, pro-albumin and hemoglobin), indicating that patients with CHF might have PEI and FE-1 could be used as an index of malnutrition in CHF." (PMID 29155861, 2017). "While results from our study suggest that measuring albumin levels is a useful tool to identify malnutrition in non-acute clinical settings, these classification cut-offs may not be appropriate." (PMID 28771192, 2017). "Whilst albumin and protein level may be useful in the assessment of malnutrition, these biomarkers are not helpful at monitoring potential therapeutic effects of nutrition." (PMID 28619005, 2017). "A negative correlation between RDW and malnutrition makers (albumin, cholesterol) was found." (PMID 27906969, 2016). "On the other hand, albumin is not a reliable biomarker for malnutrition in patients under HD." (PMID 27870908, 2016). "Furthermore, serum proteins such as albumin are good for detecting inflammatory states rather than malnutrition; the distinction between the two is important for clinicians to understand." (PMID 27174435, 2016).
malnutrition (continued). "First, negative emotions, such as depression, are known to be associated with treatment non-adherence and unhealthy lifestyle such as malnutrition and physical inactivity that may accelerate the decline in serum albumin and thus progression of CKD." (PMID 26637344, 2015). "However, it is important to emphasize that our study, similarly to all other large cohort studies, does not have data related to malnutrition and inflammation, such albumin, CRP, IL-6 or any other marker." (PMID 26091005, 2015). "In another hand, normal serum phosphorus could not be explained by malnutrition; despite their old age, nutritional markers (such as albumin and phosphatemia) were not statistically different from those in the other groups." (PMID 25123022, 2014). "Finally, the patients included in this study had normal plasma albumin levels and showed no clinical evidence of malnutrition." (PMID 23923025, 2013). "Despite the use of serum albumin level as a standard indicator of nutritional status, its sensitivity and specificity for malnutrition are not well established in HIV-infected individuals where low serum albumin often results (independently of malnutrition) from advanced HIV infection." (PMID 22532840, 2012). "According to these results, animals subjected to the dietary restriction described in this study did not present malnutrition, given that no alterations in serum albumin and total serum proteins could be observed in any of the animals." (PMID 22221448, 2012). "Additionally, the decreased level of albumin or hypoalbuminemia and total protein in TAA control rats could be due to malnutrition related to liver cirrhosis." (PMID 22649470, 2012). "The lower BMI in patients with MODS than those without MODS may be due to the presence of malnutrition since the albumin levels were also decreased in patients with MODS than those without MODS." (PMID 21187890, 2010). "Additionally, albumin is a negative acute phase reactant which would likely be diminished in many hospitalized patients who do not suffer from malnutrition." (PMID 17980023, 2007). "However, using a cutoff point of 3.5 g/dL for serum albumin as an indicator of malnutrition may not be appropriate for older individuals, particularly those who are hospitalized." (PMID 40094974, 2025). "Furthermore, the GNRI, by integrating serum albumin and body weight, may partly reflect sarcopenia rather than pure malnutrition, particularly in older patients with reduced muscle mass." (PMID 41408535, 2025). "Compared to their without malnutrition exposure risk counterparts, the with malnutrition exposure risk group exhibited significantly elevated levels of SHBG and HbA1c and reduced C-peptide, triglycerides, uric acid, hemoglobin, IGF-1, AST, ALT, weight, BMI, albumin, prealbumin, and transferrin." (PMID 39020340, 2024). "However, recent evidence suggests that in patients with hip fractures, the sharp decline in serum albumin levels may be attributed to inflammation rather than pre-existing malnutrition." (PMID 37838687, 2023). "We failed to found that the malnutrition assessed by GNRI was associated with poor survival in patients with MSA, which may due to the relatively low prevalence of malnutrition detected by GNRI, and GNRI only contains the serum albumin and body weight." (PMID 38075229, 2023). "Hence, albumin represents a surrogate of disease activity rather than a marker of malnutrition." (PMID 35267906, 2022). "Higher MaRIA was associated with more severe intestinal inflammation and lower intestinal absorptive capacity, and minors with CD were more prone to malnutrition and negative nitrogen balance, which could explain the negative correlation between MaRIA and albumin." (PMID 35571113, 2022).
malnutrition (continued). "In adults on maintenance HD, the Malnutrition Inflammation Score may be used to assess nutritional status, which, apart from the seven components included in the SGA, additionally takes into account components such as body mass index, serum albumin level, and total iron-binding capacity." (PMID 34835927, 2021). "Therefore, although the underlying mechanism of the relationship between malnutrition and cognitive function is not clear until present, the GNRI defined that using serum albumin and weight loss has been validated in exploring the association of malnutrition with cognition function in this study." (PMID 34880747, 2021). "However, there is a limitation to using serum albumin as the only nourishment state determinant, since albumin is a negative immediate that may become abnormal in states other than malnutrition, such as in chronic diseases." (PMID 33532686, 2021). "The limitations of Child-Pugh classification include that hyperbilirubinemia may be associated with a non-liver-related disease (e.g. hemolysis) and that the albumin level may be affected by a non-liver-related disease (e.g. cancer-related symptoms with malnutrition)." (PMID 33765059, 2021). "Additionally, ALB is not a nutritional biomarker if malnutrition develops in a short time." (PMID 31379941, 2019). "Notably, the lower albumin levels in this instance may have been interpreted as indicative of malnutrition if albumin was assayed on its own and prealbumin was not included." (PMID 30065944, 2018). "A sensitivity analysis restricted to patients with acute disease showed that albumin concentration for patients with high risk of malnutrition determined by MNA and SGA was not significantly lower than that for those without a risk of malnutrition (data not shown)." (PMID 28771192, 2017). "However, evidence suggests that using a cutoff point of 3.5 g/dL for serum albumin as an indicator of malnutrition may not be suitable for older people, especially those hospitalized elderly." (PMID 28771192, 2017). "A negative significant correlation of RDW with albumin and atrial fibrillation could be explained by a more frequent occurrence of both hypoalbuminemia and atrial fibrillation in patients who are in the chronic state of malnutrition." (PMID 23444243, 2013). "HD patients with severe periodontitis were 2.64 times more likely to exhibit elevated malnutrition–inflammation‐atherosclerosis (MIA) components and had lower serum albumin levels compared to those without severe disease." (PMID 41476846, 2025). "CRP and albumin are not just the components of the immune-inflammation index CAR, but they are also strong predictors of liver function, malnutrition, and eventual WL in cancer patients, which can lead to deadly cachexia." (PMID 38975012, 2024). "Among the four reported biomarkers of malnutrition, BMI and HGB displayed a positive correlation with the MNA-SF score, while TC and ALB did not exhibit a significant correlation." (PMID 38622502, 2024). "Serum albumin can be lowered by inflammation, PEW and so not just a marker of malnutrition, and the mean serum albumin was below the ISRNM advisory target level of 38 g/L in our patient cohort." (PMID 38866974, 2024). "Our discoveries showed that esophageal cancer patients without malnutrition had lower levels of the inflammatory marker CRP and higher levels of ALB than those with malnutrition." (PMID 39070256, 2024). "We used mGPS, a two-dimensional measure of malnutrition and systemic inflammation, including positive and negative acute phase reactants (CRP and albumin), as a prognostic indicator." (PMID 37836440, 2023). "However, the authors of this meta-analysis suggested that the determination of albumin alone may lead to an underestimation of the cases of minor malnutrition when the albumin concentration is still normal and may not be recognized by anthropometric and questionnaire assessments." (PMID 37571416, 2023).
malnutrition (continued). "However, lower albumin was associated with lower FSIQ in PFIC patients with native liver, suggesting that the seemingly delayed intelligence development may be influenced by malnutrition and liver dysfunctions, regardless of original disease." (PMID 36012923, 2022). "However, clinicians must recognize that albumin is a poor indicator of nutritional status since it is a negative acute phase protein and a low level may be more indicative of inflammation rather than malnutrition." (PMID 35862384, 2022). "We also observed a weak correlation between miR-511-3p and BMI (positive), albumin (positive), FFMI (negative), malnutrition grade according to the SGA scale (negative) and the NRI (positive)." (PMID 35160257, 2022). "In other words, the ALB and ALP levels of 99.49% of the population in this study were within the normal reference range, so malnutrition, inflammation and immune response do not seem like likely explanations for this association." (PMID 33993872, 2021). "The MCC does not includethe BMI or serum albumin as indicators, but agrees with the GLIM criteria and isbased on a consistent definition of malnutrition." (PMID 33836040, 2021). "The preoperative blood test showed malnutrition (ALB 3.4 g/dl, pre-albumin 19.3 mg/dl, RBP 2.0 mg/dl), anemia (Hb 10.4 g/dl), and no jaundice (total-bilirubin 0.8 mg/dl)." (PMID 34061274, 2021). "Albumin level and MNA, but not MNA SF, indicated an increasing odds of malnutrition together with decreasing eGRF." (PMID 33008315, 2020). "Albumin level and MNA, but not MNA Short Form, indicated an increased odds of malnutrition with a decrease in eGFR." (PMID 33008315, 2020). "Following 14 day repletion after malnutrition for 21 days, there was a significant increase (not significantly different from NOM group) in serum albumin concentration with insect groups, a finding consistent with previous studies." (PMID 31623146, 2019). "However, other studies have reported that albumin is not a good marker of malnutrition for elderly patients; rather, they suggest that the decrease in albumin, which acts as a binding protein, increases the circulation of unbound drugs, which may lead to adverse events." (PMID 30367604, 2018). "We recorded: demographic data, body mass index (BMI), Braden score, laboratory parameters of interest (albumin, total protein, RBC count, haemoglobin and iron levels) and presence or absence of malnutrition and pressure ulcers." (PMID 27703567, 2016). "A negative correlation observed between serum ghrelin and albumin levels with BUN and creatinine in this study, suggesting that high level of uremic toxin metabolites may lead to decreased serum ghrelin level or impair ghrelin's function, causes anorexia and malnutrition in these patients." (PMID 27433541, 2014). "Therefore, in our study, lack of significant association between biochemical parameters (such as albumin, hemoglobin, cholesterol, BUN, and creatinine) and malnutrition revealed that these parameters could not provide accurate information about nutritional status of these patients." (PMID 25032136, 2014). "Notably, since albumin is a major negative acute phase reactant, a higher inflammatory status result may explain the association between hypoalbuminemia and poor QFT results better than the malnutrition hypothesis." (PMID 21513568, 2011). "Compared with non-malnourished patients, patients with GLIM-defined malnutrition were older, had a lower BMI and SMI, had lower preoperative albumin and hemoglobin levels, had a lower 6-meter gait speed, and had a higher incidence of previous abdominal surgery." (PMID 38395798, 2024). "Unlike malnutrition, in which abnormalities are induced by an inadequate diet, PEW refers to abnormalities that cannot be corrected solely by changing the diet and are induced, usually, by inflammation and accompanied by decreased serum albumin levels." (PMID 39195556, 2024).